PRMT5 (protein arginine methyltransferase 5)
Diseases named in the same sentence as PRMT5 in open-access papers (continued):
Sharing a sentence is not in itself a finding about the gene and the disease.
lymphoma (continued). "In canine lymphomas of various histopathological subtypes (n = 337), PRMT5 immunoreactivity was more variable in intensity and subcellular localization with strong cytoplasmic expression in 42.40% of samples." (PMID 33989303, 2021). "To validate canine lymphoma as a useful comparison to human lymphoma while validating PRMT5 as a rational therapeutic target in canine lymphoma, we evaluated the prevalence of PRMT5 expression and correlation with histological subtype in canine lymphomas." (PMID 33989303, 2021). "In human lymphoma, PRMT5 is a known driver of malignant transformation and oncogenesis, however, the expression and role of PRMT5 in canine lymphoma has not been explored." (PMID 33989303, 2021). "While PRMT5 was expressed in all tumors, the level of expression was variable, with over 42% of canine lymphomas showing strong expression based on immunohistochemical staining." (PMID 33989303, 2021). "PRMT5 promotes the survival of lymphoma cells, and its inhibitory effect induces lymphoma cell death." (PMID 34513846, 2021). "Although the safety and efficacy of the use of PRMT5 inhibitors for the treatment of human lymphoma is currently being established in ongoing clinical trials, further preclinical investigation is warranted." (PMID 33989303, 2021). "In conclusion, PRMT5 overexpression is related to the development of BLV infection with a high proviral load and lymphoma stage and PRMT5 inhibition enhances BLV gene expression." (PMID 32560231, 2020). "PRMT5 protein is overexpressed in many cancer types, including lymphoma, glioma, breast and lung cancer." (PMID 29946150, 2018). "Treatment of lymphoma cells with PRMT5 inhibitor induced G1 arrest and subsequent apoptosis in a subset of cell lines." (PMID 29946150, 2018). "Impending evidence also suggest a role of PRMT5 in tumorigenesis including leukemia, lymphoma, and in many solid tumors, making PRMT5 an attractive anticancer target." (PMID 29718323, 2018). "The cellular potency of GSK3326595 (SDMA EC50) was further assessed in a panel of breast and lymphoma cell lines representing a range of sensitivities to PRMT5 inhibition." (PMID 29946150, 2018). "GSK3326595 is a selective and potent inhibitor of PRMT5 that is currently being tested in a Phase I trial in patients with refractory solid tumours and lymphoma (NCT02783300, clinicaltrials.gov)." (PMID 29946150, 2018). "This is well in line with the findings that PRMT5 overexpression triggered the suppression of the transcription of the pRb in leukemia and in lymphoma cell." (PMID 28074910, 2017). "Recently, PRMT5 over-expression was identified to be involved in the pathogenesis of hematologic (lymphoma) and solid tumors (melanoma, astrocytomas)." (PMID 26729154, 2015). "Both PRMT5 protein and RNA were upregulated in all T-cell leukemia/lymphoma cell lines compared to naïve T-cells." (PMID 26729154, 2015). "The type II arginine methyltransferases PRMT5, that catalyze ω-NG-monomethylation and ω-NG,NG′-symmetric dimethylation, is overexpressed in lymphoid cancer cell lines and its level correlates with increased symmetric methylation of histones H3R8 and H4R3." (PMID 25968566, 2015). "Recent reports have indicated PRMT5 over-expression as relevant to the pathogenesis of many cancers, including lymphomas, melanomas, and astrocytomas." (PMID 26729154, 2015). "PRMTs, like the coactivator-associated arginine methyl-transferase (CARM1) and PRMT5, have been described to play an important role in cancer as their expression increases in breast and prostate cancers, for CARM1, and lymphoma, for PRMT5." (PMID 23016851, 2013).
lymphoma (continued). "It has been shown that overexpression of PRMT5 in lymphoma is correlated to a global increase of H4R3 and H3R8 symmetric dimethylation, which likely suppresses the expression of the tumor suppressor gene ST7 to affect tumorigenesis." (PMID 19521535, 2009). "PRMT5 overexpression has been reported in many malignancies, including glioblastoma, melanoma, ovary, lung, breast, stomach, and lymphoma, which correlates with its ability to directly methylate several transcription factors." (PMID 41154773, 2025). "PRT543 is a PRMT5 inhibitor used for solid tumors and lymphoma." (PMID 40869229, 2025). "RBL2 belongs to the retinoblastoma protein family and is repressed by PRMT5 in lymphoma cells." (PMID 39478125, 2024). "Upregulation of PRMT5 is documented in lymphoma and is herein observed in CLL-to-RT progression, yet mechanisms by which this occurs remain unknown." (PMID 36609611, 2023). "Left untreated, engrafted mice succumbed to expanding leukemia/lymphoma with a median overall survival of 67 days (range 66–75 days), and tumor histology was similar to that of transgenic Eμ-PRMT5/TCL1 mice with spleen and lymph node involvement and bone marrow infiltration." (PMID 36609611, 2023). "For example, high PRMT5 expression drives transcriptional silencing of tumor‐suppressing miR33b, miR96, and miR503 via histone 3 dimethylation in their promoter regions, and then reinforces lymphoma cell growth and survival." (PMID 36999124, 2023). "Furthermore, PRMT5 increases de novo syntheses of key lymphoma-drivers, MYC and CYCLIN D1 by repressing miR-33b, miR-96, and miR-5038,10." (PMID 36167829, 2022). "PRMT5 expression correlates with MSI2 expression in lymphoma patients." (PMID 36167829, 2022). "Collectively, these data suggest selective targeting of PRMT5 may have a therapeutic value in lymphoma." (PMID 36167829, 2022). "Moreover, combining PRMT5 inhibition with MSI2 or BCL-2 inhibitors blocks the translation of key drivers of lymphoma, c-MYC and BCL-2, inhibiting cell growth." (PMID 36167829, 2022). "Thus, we propose a therapeutic strategy in lymphoma that combines PRMT5 with MSI2 or BCL-2 inhibition." (PMID 36167829, 2022). "Moreover, Type I PRMT and specific PRMT5 inhibitors have shown strong results both on leukemia and lymphoma cell lines and in several mouse models of hematological malignancies, thus, explaining their use in clinical trials." (PMID 36358861, 2022). "Given the relevance of PRMT5 to lymphomagenesis in humans, we hypothesized that PRMT5 would be overexpressed in canine lymphomas." (PMID 33989303, 2021). "PRMT5 immunohistochemistry of canine lymphoma tissue microarrays." (PMID 33989303, 2021). "To explore canine lymphoma as a useful comparison to human lymphoma while validating PRMT5 as a rational therapeutic target in both, we characterized expression patterns of PRMT5 in canine lymphoma tissue microarrays, primary lymphoid biopsies, and canine lymphoma-derived cell lines." (PMID 33989303, 2021). "We have established that PRMT5 exhibits variable overexpression in all subtypes of canine lymphoma." (PMID 33989303, 2021). "Besides, PRMT5 regulates pro-survival genes expressions by upregulating WNT/β-CATENIN and AKT/GSK3β signaling pathways; and inhibiting PRMT5 can induce lymphoma cell death." (PMID 34124017, 2021). "Importantly, knock-down of PRMT5 upregulated pRB protein levels, impaired proliferation of lymphoma cells, and induced cell death as detected by caspase-3 cleavage." (PMID 35008680, 2021).
lymphoma (continued). "In lymphoma cell lines, PRMT5 mediates epigenetic repression of AXIN2 and WIF1, leading to indirect activation of AKT, which could be another alternative upstream mechanism; however, this has not been investigated in PDAC." (PMID 34680285, 2021). "Thus, conclusions comparing relative PRMT5 expression and cellular localization in less common histologic subtypes of lymphoma must be made with caution." (PMID 33989303, 2021). "Additionally, recent studies show that PRMT5 promotes survival of lymphoma cells via WNT and AKT-mediated proliferation signalling." (PMID 35582230, 2020). "This strongly indicates that PRMT5 upregulation continues until the lymphoma stage of BLV." (PMID 32560231, 2020). "While the exact biology of PRMT5 inhibitors remains unclear, advanced compounds are now in clinical trial against lymphoma and solid tumors." (PMID 31817960, 2019). "Nevertheless, control shRNAs targeting essential genes (Rpa1, Rpa3 and Polr2b;) were consistently depleted in all four replicates, as were shRNAs targeting genes that either cooperated with Myc (Prmt5 and Odc) or belonged to known oncogenic pathways in Eμ-myc lymphomas (Adsl and Rsl24d1)." (PMID 27635472, 2016). "Increased PRMT5 levels have been noted in cell lines derived from a variety of human lymphomas, implying that PRMT5 might function in the context of multiple oncogenic drivers." (PMID 26425661, 2015). "Indeed, we found PRMT5 levels were upregulated during T-cell transformation and in established lymphocytic leukemia/lymphoma cell lines." (PMID 26729154, 2015). "We hypothesized that the resistance to GSK-591 observed in some lymphoma cell lines and the modest effect of PRMT5 inhibitor in vivo are likely related to the induction of feedback survival mechanisms and/or due to the coexistence of parallel survival pathways." (PMID 36167829, 2022). "In addition, we have previously shown that PRMT5 associates with an NF‐κB transcriptional repressor complex containing HDAC3, which promotes deacetylation of H3K14 lysine, and triggers gene silencing in lymphoma cells." (PMID 33462997, 2021). "PRMT5 has been regarded as an oncogene, because it is overexpressed in various human lymphomas and solid tumors; PRMT5 promotes cancer cell survival and proliferation, suggesting that it may be important for regulating these processes also in non-neoplastic cells." (PMID 32328070, 2020). "Therefore, PRMT5 is a rational target for treating lymphoma." (PMID 35582230, 2020). "Finally, we investigated whether the change in PRMT5 expression in BLV-infected cattle occurred in the lymphoma stage of disease." (PMID 32560231, 2020). "Also, PRMT5 maintained the expression of the AP1 protein BATF3, which has been described as an upstream MYC-activator in Hodgkin lymphomas and T cell leukemia and is known to cause lymphomas of mature B cells in mice." (PMID 32555249, 2020). "In our screen, a large fraction of lymphoma, breast and multiple myeloma cell lines exhibited close to complete growth inhibition or a net cell death phenotype, suggesting that these tumour types are the most vulnerable to the attenuation of PRMT5 activity in vitro." (PMID 29946150, 2018). "Currently, several strategies involving the combination of BCL6 inhibitors with several agents, including PRMT5 inhibitors, EZH2 inhibitors, STAT3 inhibitors and chemotherapy drug doxorubicin, have been explored for the treatment of lymphomas." (PMID 39815148, 2025). "BCL6 has been reported to co-regulate GC formation and lymphoma cell survival with EZH2 and PRMT5, respectively." (PMID 39815148, 2025).
lymphoma (continued). "GFI-1, Sin3A, PRMT5 and CCAR2 genes were uniformly expressed at high levels also in SUP-M2 cells, thus confirming their potential relevance in lymphoma." (PMID 39478125, 2024). "Protein arginine methyltransferase 5 (PRMT5), a type II PRMT enzyme, is directly involved in the pathogenesis of several different lymphomas through transcriptional regulation of related oncogenes." (PMID 37511495, 2023). "PRMT5 contributed to the disease by methylating BCL6 at R305, which is necessary for the full transcriptional repressive effects of BCL6 in lymphoma." (PMID 37461162, 2023). "In their results, EPZ015866 shows lower PRMT5 IC50 and lymphoma cell line proliferation IC50 values than EPZ015666, suggesting a greater inhibitory effect on PRMT5." (PMID 36901758, 2023). "In summary, our data indicate that PRMT5 promotes CLL development, facilitates CLL progression to aggressive lymphoma through altered epigenetic programming, and provides a preclinical model and a therapeutic candidate to study CLL-to-RT progression." (PMID 36609611, 2023). "Therefore, to inhibit the PRMT5/MSI2/c-MYC/BCL-2 axis we proposed two drug combination strategies; the first one consists of targeting PRMT5 in combination with a MSI2 inhibitor, which results in loss of c-MYC and BCL-2 translation cell-cycle regulators in lymphoma cells." (PMID 36167829, 2022). "We tested if PRMT5 and MSI2 inhibitors alone or in combination affected c-MYC mRNA in lymphoma cells." (PMID 36167829, 2022). "PRMT5 is overexpressed in MCL, GC-DLBCL, and activated B cell-like DLBCL (ABC-DLBCL) cell lines and clinical samples as well as in mouse primary lymphoma cells." (PMID 35463343, 2022). "PRMT5 knockdown reactivates the RB1/RBL2-E2F tumor suppressor pathway and antagonizes cyclin D1-CDK4/6 signaling, which in turn leads to lymphoma cell death." (PMID 35463343, 2022). "In the most aggressive forms of lymphoma, MSI2 is overexpressed and cooperates with PRMT5 in maintaining c-MYC and BCL-2, which confers resistance to PRMT5 inhibition." (PMID 36167829, 2022). "The second strategy utilizes dual targeting of PRMT5 and BCL-2, using GSK-591 and venetoclax, that exhibits potent anti-tumor efficacy and induction of apoptosis across a wide range of lymphomas." (PMID 36167829, 2022). "Compared to ND fractioned B- and T-lymphocyte subsets in peripheral blood, all canine lymphoma cell lines showed higher levels of MYC and PRMT5 protein." (PMID 33989303, 2021). "Higher expression of miR-19a, miR-25, miR-32, miR-92b and miR-96 were found to target protein arginine methyltransferase 5 (PRMT5) in leukaemia and lymphoma cells." (PMID 33050637, 2020). "First, we focused on the correlation between the PRMT5 expression level and BLV PVL, an index of virus infectivity, in peripheral blood from infected animals in various stages, such as the lymphoma and asymptomatic stages." (PMID 32560231, 2020). "The fold-change in PRMT5 expression was 1.12 ± 0.62 in BLV-negative cattle, 1.48 ± 0.66 in the asymptomatic group, and 2.45 ± 1.1 in the lymphoma group." (PMID 32560231, 2020). "We found PRMT5 expression was upregulated during HTLV-1-mediated T-cell transformation, as well as in established lymphocytic leukemia/lymphoma cell lines and ATLL patient PBMCs." (PMID 26729154, 2015). "PRT382 demonstrated optimal enzymatic kinetics in vitro, producing an IC50 of 2.8 nM in filtration binding assays with recombinant human PRMT5/MEP50 and histone H2A as the protein substrate, and an IC50 of 27 nM in a reducing sDMA assay in the Granta-519 lymphoma cell line." (PMID 36609611, 2023). "Further, inhibition of PRMT5 in B cell lymphoma resulted in markedly upregulation of BCL6 target genes, and concomitant inhibition of both BCL6 and PRMT5 exhibited synergistic killing of BCL6‐expressing lymphoma cells." (PMID 37461162, 2023).
lymphoma (continued). "Researchers have investigated the relationship between PRMT5 and Wnt/β-catenin signalling as well as AKT/GSK3β proliferative signalling in three different types of NHL cell lines, clinical samples, and mouse primary lymphoma cells." (PMID 36224652, 2022). "We have recently shown that PRMT5 promotes WNT/β‐CATENIN proliferative signalling through transcriptional repression of pathway antagonists, AXIN2 and WIF1, in three different types of lymphoma cells." (PMID 33462997, 2021). "Similar to human lymphoma, treatment of canine lymphoma cell lines showed a substantial decrease in global SDMA and H4R3me2s with minimal effect to PRMT5 expression or asymmetric dimethyl arginine (ADMA) as expected with selective inhibition of PRMT5." (PMID 33989303, 2021). "Furthermore, an arginine-N-methyltransferase, PRMT5, has shown positive correlation with BLV infection with a high pro-viral load and lymphoma stage." (PMID 33917549, 2021). "We compared PRMT5 expression at the RNA level among three groups of cattle: 20 BLV-negative cattle, 42 BLV-infected but clinically normal cattle, and 20 BLV-infected cattle with lymphoma." (PMID 32560231, 2020). "For instance, the type-II protein arginine methyltransferase, PRMT5, activates Wnt signaling and Wnt/ β-CATENIN target gene expression by differentially modulating the promoter occupancy by co-activators and co-repressors in lymphoma cells." (PMID 31497020, 2019). "In our lymphoma dataset, the levels of PRMT5 and SDMA did not correlate with anti-proliferative activity." (PMID 29946150, 2018). "Our data highlight the potential of PRMT5 inhibition as a treatment approach for human cancers and supports the progression of GSK3326595 to clinical trials in cancer patients with solid tumours and lymphoma (NCT02783300)." (PMID 29946150, 2018). "PRMT5 has been shown to be over-expressed in BL cell lines; to suppress the retinoblastoma family of tumour suppressors in leukaemia and lymphoma cells; and to mediate CCND1-dependent neoplastic growth in a mouse lymphoma model." (PMID 25436604, 2012). "In addition, PRMT5, like EZH2, is required for GC formation and lymphoma survival through its interaction with BCL6, and thus, like EZH2, may also be important in the maintenance of epigenetic dysregulation in FL." (PMID 34193230, 2021). "For example, PRMT5 could modify H3R8 and H4R3 in the promoter region of the tumor suppressor Rb, leading to silencing of Rb expression and the subsequent proliferation of leukemia and lymphoma cells." (PMID 30922330, 2019). "To investigate the correlation between PRMT5 expression and BLV PVL, we collected blood samples from 62 cows which were asymptomatic and had not developed symptoms of lymphoma at the time of blood collection." (PMID 32560231, 2020). "Furthermore, MSI2 and PRMT5 protein abundance are lower in non-malignant B cells and de novo MCL and DLBCL primary samples compared to relapsed MCL, relapsed DLBCL, and lymphoma cell lines." (PMID 36167829, 2022).